HSP90AA5P (heat shock protein 90 alpha family class A member 5, pseudogene)
Description:
Putative molecular chaperone that may promote the maturation, structural maintenance and proper regulation of specific target proteins.
Gene: Processed pseudogene on chromosome 3 (184,115,352 to 184,117,898, forward strand). Ensembl gene ENSG00000205955.
Subcellular location: Cytoplasm